BRCA1 (BRCA1 DNA repair associated)
Diseases named in the same sentence as BRCA1 in open-access papers (continued):
Sharing a sentence is not in itself a finding about the gene and the disease.
ovarian tumors (continued). "A total of 65 genes were differentially expressed between BRCA1/2-mutated and non-mutated ovarian tumours, and 34 genes were differentially expressed between BRCA1-mutated and non-BRCA-mutated ovarian tumours." (PMID 33081408, 2020). "A further 4079 probes were differentially expressed between noncancerous fallopian tubes from BRCAx and BRCA1-associated ovarian tumours." (PMID 33081408, 2020). "In fact, PARPi are used in clinic as synthetic lethal monotherapy for BRCA-mutant ovarian tumors that are deficient in HRR of DSBs, although it needs to be confirmed whether the BRCA1 mutation affects the functional state of BRCA in H727 cells." (PMID 29872498, 2018). "5382insC produces a C-terminal truncated BRCA1 commonly encountered in breast and ovarian tumors." (PMID 29459887, 2018). "BRCA1 and BRCA2 mutations are associated with a higher risk of breast and ovarian tumors." (PMID 29026449, 2017). "With the exception of BRCA1 germline mutation-associated ovarian tumors, the proportion of tumors without locus-specific LOH was nearly identical in the Penn and TCGA data sets." (PMID 28831036, 2017). "For the evaluation of our approach, 127 ovarian tumor samples derived from 96 patients were tested: 29 with a BRCA1, 14 with a BRCA2, and 53 without a germline mutation in either gene." (PMID 27767231, 2017). "Koul and colleagues hypothesized that BRCA1 might have a possible role in ovarian tumors metastasizing to the brain, which is mostly in line with our mutational results." (PMID 28497333, 2017). "Eight of 23 BRCA1 germline mutation-associated breast (one without and seven with locus-specific LOH) and three of 15 BRCA1 germline mutation-associated ovarian tumors (two without and one with locus-specific LOH) had somatic promoter methylation." (PMID 28831036, 2017). "Levels of methylation in ovarian tumors quantitatively correlated with decreased BRCA1 expression." (PMID 25986046, 2015). "Also borderline BRCA1 carriers ovarian tumors are very rare, which reinforces the increasing evidence that BRCA1 mutations do not play a role in the development of this type of tumors." (PMID 25136623, 2014). "BRCA1 protein and mRNA levels in ovarian tumors are decreased or absent in as many as 90% of patient cases without evidence of germline BRCA1 mutations or family history of BRCA-associated diseases." (PMID 25136623, 2014). "Either genetic or somatic mutations of BRCA1 and BRCA2 are found in approximately 20% of all ovarian tumors; when considering all kinds of BRCA1/2 alterations, including mutations, these have been reported in up to 82% of ovarian tumors." (PMID 25136623, 2014). "The loss of the BRCA1 wild-type allele inherited from the unaffected parent through LOH represents the event that initiates the tumorigenesis process observed in primary breast and ovarian tumors." (PMID 25264427, 2014). "In both Brca1-deficient models, treatment with olaparib resulted in less differentiated SEOC with increased nuclear size and pleomorphism compared to the well to moderately differentiated papillary structures of the ovarian tumors in vehicle-treated mice." (PMID 24748377, 2014). "These loci may lead to an improved understanding of the etiology of breast and ovarian tumors in BRCA1 carriers." (PMID 23544013, 2013). "Although somatic mutations in BRCA1 are rare, reduced or absent protein expression has been observed in up to 90% of sporadic ovarian tumors indicating that epigenetic factors, mainly promoter hypermethylation, are also involved in its regulation." (PMID 20046869, 2009).
ovarian tumors (continued). "Summary of the SAM analysis comparing miRNA expression profiles between high grade serous carcinomas of different BRCA1/2 status and between ovarian tumors of different histopathologic types, with a false-discovery rate (FDR) <5% (miRNA in bold italic are associated with a FDR <0.1%)." (PMID 19798417, 2009). "Apart novel drugs like PARP inhibitors, these findings may allow a different and more rational approach for the treatment of BRCA1/2 related ovarian tumors by currently available drugs." (PMID 19825178, 2009). "However, reduced BRCA1 protein expression is detected in high-grade sporadic breast and ovarian tumors, suggesting that epigenetic downregulation of BRCA1 contributes to their aggressive clinical course." (PMID 18241344, 2008). "In addition, 18 breast or ovarian tumors (18/70, 26%), including the three cases with germline BRCA2 mutations, exhibited a predominant “BRCAness” mutational signature, an indicator of functional BRCA1/BRCA2 deficiency." (PMID 29464067, 2018). "More recently the same authors have produced a systematic review on all published studies on this topic from 1990 to 2008 leading to the hypothesis of a possible role of BRCA1 as biomarker predictive of treatment response in hereditary and sporadic ovarian tumors." (PMID 19825178, 2009). "In OC, KRAS was downregulated, whereas the other hub genes CTNNB1, BRCA1, and JUN were upregulated in ovarian tumor tissues." (PMID 41186627, 2025). "Pathogenic large rearrangements were also analyzed in 20,000 ovarian tumors with NGS and were detected in 0.7% of the cases, which reflected a total of 6.3% of all BRCA1/2 TPVs detected in the cohort." (PMID 38730634, 2024). "MeSH descriptors and keywords, such as “BRCA1 genes,” “BRCA2 genes”, “Latin America”, and “ovarian neoplasms” were used, along with terms related to socioeconomic and health factors." (PMID 39338246, 2024). "Transcriptomic and pathway analyses comparing BRCA1-mutant, BRCA2-mutant, and homologous recombination wild-type ovarian tumors showed differential regulation of the Wnt/β-catenin pathway." (PMID 39028933, 2024). "The molecular mechanisms that confer this differential clinical profile between BRCA1- and BRCA2-mutant ovarian tumors are not well understood." (PMID 39028933, 2024). "In an attempt to purify these groups, samples that were misclassified were excluded from further analysis, leaving only 23 familial (13 BRCA1, 10 BRCA2) and 14 sporadic ovarian tumour samples." (PMID 33081408, 2020). "BRCA1-mutant HGSOC/TNBC cells and ovarian tumor tissues showed increased expression of Ubc9 compared to BRCA1 reconstituted HGSOC, normal mammary epithelial cells and matched normal ovarian tissues." (PMID 28164176, 2016). "Five new BRCA1 mutant ovarian tumors and four new BRCA2 mutant ovarian tumors were analyzed compared to the previous studies." (PMID 25437005, 2014). "The HR-pathway and expression of BRCA1 and BRCA2 is extremely relevant in ovarian tumors, and we observed that there is detectable expression of miR-1255b, miR-148b*, and miR-193b* in a panel of ovarian tumor lines." (PMID 24843000, 2014).
ovarian tumors (continued). "The best-known hereditary cancer genes, BRCA1 and BRCA2, contribute to substantial share of breast and ovarian tumor incidence around the globe, and have been studied with significant level of comprehension." (PMID 21819606, 2011). "Nevertheless, in the only reported case of combined germ-line heterozygosity for BRCA1 and NBS1 genes in ovarian tumor, there was somatic inactivation of the NBS1 gene, whereas the BRCA1 gene remained intact." (PMID 22649661, 2010). "Despite the observed associations between BRCA1 and BRCA2 germline pathogenic variant status with ovarian tumour characteristics, currently VUS interpretation efforts do not consider ovarian tumour pathology." (PMID 37076566, 2023). "Negative (immunoglobulin G isotype) and positive (ovarian tumor section) controls showed no signal or strong nuclear and cytosolic BRCA1 staining, respectively." (PMID 31940810, 2020). "Another study has found that none of the ovarian tumors with BRCA1 promoter hypermethylation demonstrate BRCA1 protein expression by immunohistochemistry, being consistent with the silencing of the BRCA1 gene." (PMID 32483276, 2020). "Moreover, we analyzed the differential expression of SORBS2 in (a) BRCA1 mutant and BRCA2 mutant tumor tissues compared with wild-type tumor tissues; (b) CCNE1high and CCNE1low ovarian tumor tissues in TCGA dataset." (PMID 29548303, 2018). "HRD-Mean scores were not significantly different between BRCA1 and BRCA2 germline mutation-associated breast and ovarian tumors." (PMID 28831036, 2017). "Furthermore, deletion of miR-1255b, miR-148b*, and miR-193b* in independent cohorts of ovarian tumors correlates with significant increase in LOH events/chromosomal aberrations and BRCA1 expression." (PMID 24843000, 2014). "As with short term treatment, prolonged treatment of orthotopic Brca1-wild type ovarian tumors with cisplatin, olaparib or their combination did not result in tumor regression or tumor growth arrest." (PMID 24748377, 2014). "Ovarian tumors deficient in Brca1 respond to treatment with cisplatin and olaparib, a PARP inhibitor, whereas Brca1-wild type tumors are non-responsive to treatment, recapitulating the relative sensitivities observed in patients." (PMID 24748377, 2014). "The lack of ovarian tumors is consistent with previous studies demonstrating that inactivation of Brca1 alone is insufficient for malignant transformation in the mouse ovary." (PMID 20046879, 2009). "Recent work suggests that BRCA1 inactivation contributes to ovarian tumor development by cell non-autonomous mechanisms." (PMID 20046879, 2009). "Recent data indicate that BRCA1/2-associated HGSOCs do not show inferior outcomes when treated by NACT before the surgery, while primary surgical intervention is clearly the best approach in sporadic ovarian tumors." (PMID 33536037, 2021). "The heterogeneous nature of ovarian tumors, however, may not enable a full accuracy in the classification of the samples into BRCA1/2 positive/negative profile." (PMID 32483276, 2020). "Interestingly, it has been demonstrated that there was increased BRCA1 protein expression, in the absence of BRCA1 reversion mutation, in two of four tumors carrying BRCT domain mutations in ovarian tumor samples resistant to carboplatin." (PMID 30669514, 2019). "Both BRCA1 and BRCA2 germline mutation-associated breast and ovarian tumors had a significantly lower proportion of the aging signature (Signatures 1 and 5) compared to nonBRCA breast and ovarian tumors." (PMID 28831036, 2017). "Moreover, they showed that 12 of 81 (~15%) ovarian tumors in patients without a family history of OC had evidence of BRCA1 promoter methylation." (PMID 25136623, 2014).
ovarian tumors (continued). "We found that both BRCA1 and BRCA2 ovarian tumors without locus-specific LOH treated with adjuvant platinum based chemotherapy have lower overall survival than tumors with locus-specific LOH, at rates similar to sporadic tumors." (PMID 28831036, 2017).
colorectal cancer (150 papers, 2001 to 2025). A primary or metastatic malignant neoplasm that affects the colon or rectum. "The results of this research point to a possible connection between infection with HPV and BRCA1/2 mutations in the occurrence of colorectal cancer in the Egyptian population, which has a mixed ethnic background." (PMID 37804357, 2023). "In a systematic review of 18 studies and a meta-analysis of 14 studies, the risk of colorectal cancer was shown to be moderately elevated in BRCA1 (a 1.49-fold higher risk of CRC in BRCA1 mutation carriers) but not in BRCA2 mutation carriers." (PMID 37761360, 2023). "This study aimed to identify BRCA1/2 mutational patterns in the tissue and blood of Egyptian colorectal cancer (CRC) patients and to study the possible correlation of this mutational pattern with Human papillomavirus (HPV) infection." (PMID 37804357, 2023). "Further studies should focus on the situation of male BRCA1 or BRCA2 mutation carriers or on the situation of mutation carriers in other hereditary diseases (e.g. familial colorectal cancer)." (PMID 34635688, 2021). "Recently, an increased risk of colorectal cancer has been demonstrated in germline BRCA1/2 mutation carriers." (PMID 32377194, 2020). "For common cancers, such as breast and colorectal cancers, mutations in high-risk predisposition genes BRCA1/2 and mismatch repair genes are rare, accounting for a small proportion of the particular cancers (depending on population, approximately 1%)." (PMID 32992489, 2020). "The BeSHG guidelines for managing HBOC indicate that BRCA1 mutation carriers have an increased risk of early-onset colorectal cancer (diagnosis <50 years), but the increase is small." (PMID 32655641, 2020). "Ending long-lasting debate, a new meta-analysis has clearly shown a statistically significant increased risk of colorectal cancer development in carriers of BRCA1 mutations." (PMID 32377194, 2020). "Since colorectal cancer can be prevented through colonoscopy screening and removal of adenomatous polyps the authors proposed that all female BRCA1 mutation carriers should be offered colonoscopy at 3- to 5-year intervals between the ages of 40 and 50 years." (PMID 30136106, 2019). "As such, a patient with a BRCA1 mutation undergoing surgical management of colorectal cancer may opt to pursue prophylactic hysterectomy with salpingo-oophorectomy at the same time considering this mutation." (PMID 37509234, 2023). "In summary, this paper describes the outcome of germline FFPE testing of the BRCA1/2 genes and a panel of 13 genes linked to inherited colorectal cancer susceptibility in deceased index cases, where previously it had not been possible to offer diagnostic testing to a living affected relative." (PMID 33654310, 2021). "Some colorectal epidemiological studies speculate a greater incidence of colorectal cancer in women younger than 50 years carrying a BRCA1 mutation." (PMID 33198203, 2020). "To assess whether there is a higher incidence of BRCA1/2 mutations in MC tumors than in AC tumors, we performed an analysis of a cohort of targeted sequencing of 1134 metastatic colorectal cancer samples (hereby the MSKCC database)." (PMID 32377194, 2020). "Furthermore, any breast-colorectal GWAS signal was less likely to be due to syndromic cases since all cases carrying BRCA1 or BRCA2 or known colorectal cancer susceptibility gene mutations were excluded from the GWAS." (PMID 29698419, 2018). "Furthermore, a slightly increased risk for uterine and cervical cancer as well as colorectal cancer has also been reported for BRCA1 mutation carriers." (PMID 23164213, 2012). "In the BRCA1 gene, four c.5382insC mutation carriers were found in early-onset cases: 3 of them did not have a family history of cancer, one patient's grandfathers had gastric cancer, uncle had colorectal cancer, nieces had melanoma and uterus cancer." (PMID 20380699, 2010).
colorectal cancer (continued). "It is presently unclear whether carriers of BRCA1 mutations have an increased risk for colorectal cancer (CRC)." (PMID 11207040, 2001). "Moreover, it has been confirmed that BRCA1 mutations also raise the risk of colorectal cancer." (PMID 35769138, 2022). "Moreover, the risk of colorectal cancer conferred by mutations in BRCA1 is recently increasing, implying that BRCA1 might play a key role in colorectal tumorigenesis." (PMID 28381275, 2017). "Firstly, we assessed the expression of HA and its main receptor, CD44, alongside BRCA1 and 2 to explore potential relationships in breast and colorectal cancer tissues." (PMID 41373491, 2025). "This study investigates the link between HA metabolism and BRCA1/2 expression in breast and colorectal cancers." (PMID 41373491, 2025). "Disease processes associated with these BRCA1/Kaiso gene promoters indicate that BRCA1 is functionally linked to a Kaiso-directed programme of RNAP2-mediated gene transcription and likely associated with colorectal cancer development and maintenance." (PMID 40460875, 2025). "Colorectal cancer exhibited the lowest and second-lowest rates of BRCA1/2 and oHRR biallelic alterations, correlating with its lower HRD scores." (PMID 40420266, 2025). "Among them, three TF genes, E2F1, E2F3, and BRCA1, were validated as differentially expressed in databases of psoriasis and colorectal cancer, confirming their designation as hub TFs." (PMID 39045407, 2024). "TCGA analysis showed that the expression level of ESCO2 positively correlated with 53BP1 and BRCA1 in colorectal cancer samples." (PMID 37377435, 2023). "In subgroup analysis, colorectal cancer patients had an increased odds of BRCA1 (OR = 1.48, 95% CI = 1.10–2.01, P = 0.01) and BRCA2 (OR = 1.56, 95% CI = 1.06–2.30, P = 0.02) mutations." (PMID 37644384, 2023). "These criteria were primarily designed to detect high probabilities for BRCA1/2 or mismatch repair gene alterations in patients with breast, ovarian or colorectal cancer." (PMID 37528288, 2023). "A significant increase in the frequency of BRCA1 and BRCA2 mutations was observed in patients with colorectal cancer [OR = 1.34, 95% confidence interval (CI) = 1.02–1.76, P = 0.04]." (PMID 37644384, 2023). "Unadjusted odds ratios (ORs) were used to estimate the probability of Breast Cancer Type 1 Susceptibility gene (BRCA1) and Breast Cancer Type 2 Susceptibility gene (BRCA2) mutations in colorectal cancer patients." (PMID 37644384, 2023). "The occurrence of first colorectal cancer followed by second colorectal cancer have been commonly identified with BRCA1/BRCA2, and MMR genes." (PMID 34556087, 2021). "Of the 180 FFPE samples tested, 134 were BRCA1/2 panel analyses and 46 were inherited colorectal cancer panel analyses." (PMID 33654310, 2021). "We first confirmed that knockdown of β‐catenin in the APC‐mutant colorectal cancer cell line COLO320HSR markedly reduced the expression of BRCA1, FANCD2, and RAD51." (PMID 33660437, 2021). "These xenotransplants were analyzed by a certified pathologist who confirmed that BRCA1-KO fibroblasts displayed colorectal cancer phenotype as judged by the expression of specific markers (CK20, CEA, CDX2, AE1/AE3)." (PMID 31200749, 2019).